ENAH (ENAH actin regulator)
Description:
Ena/VASP proteins are actin-associated proteins involved in a range of processes dependent on cytoskeleton remodeling and cell polarity such as axon guidance and lamellipodial and filopodial dynamics in migrating cells. ENAH induces the formation of F-actin rich outgrowths in fibroblasts. Acts synergistically with BAIAP2-alpha and downstream of NTN1 to promote filipodia formation (By similarity).
Synonyms: MENA; FLJ10773; NDPP1; ENA
Tractability: Small molecule: a structure with a bound ligand is known. Antibody: its Gene Ontology location is reachable by antibodies, with high confidence. PROTAC: ubiquitination databases record sites on it; its protein half-life has been measured.
Gene: Protein-coding gene on chromosome 1 (225,486,765 to 225,653,298, reverse strand). Ensembl gene ENSG00000154380.
Subcellular location: Cytoplasm; Cytoplasm, cytoskeleton; Cell projection, lamellipodium; Cell projection, filopodium; Synapse; Cell junction, focal adhesion
Subcellular location (Human Protein Atlas): Cytosol; Focal adhesion sites; Plasma membrane
Pathways (Reactome):
Developmental Biology: Signaling by ROBO receptors
Immune System: Generation of second messenger molecules
Gene Ontology:
Molecular function: protein binding; WW domain binding; profilin binding; protein domain specific binding
Biological process: actin polymerization or depolymerization; actin polymerization-dependent cell motility; axon guidance; postsynaptic cytoskeleton organization
Cellular component: cytosol; focal adhesion; plasma membrane; cytoplasm; cytoskeleton; filopodium; GABA-ergic synapse; lamellipodium; postsynapse; synapse
Genetic constraint (gnomAD): Loss-of-function variants: 16 observed, 57.39 expected, observed/expected ratio (o/e) 0.28, 90% interval 0.19 to 0.42. The upper end of that interval is the gene's LOEUF score, 0.42, which puts it in group 1 of 6, group 1 being the genes least tolerant of losing a copy. Missense variants: 435 observed, 545.44 expected, observed/expected ratio (o/e) 0.8, 90% interval 0.74 to 0.86. Synonymous variants: 183 observed, 193.52 expected, observed/expected ratio (o/e) 0.95, 90% interval 0.84 to 1.07.
Homologues: Orthologues: chimpanzee ENAH (98% identical), macaque ENAH (97% identical), pig ENAH (93% identical), rat Enah (88% identical), dog ENAH (87% identical), mouse Enah (87% identical), guinea pig ENAH (85% identical), tropical clawed frog enah (76% identical), rabbit ENAH (75% identical), zebrafish enah (71% identical), Drosophila melanogaster ena (36% identical), Caenorhabditis elegans unc-34 (12% identical), and 1 more. Paralogues in human: EVL (39% identical), VASP (34% identical), SPRED2 (14% identical), SPRED1 (14% identical), SPRED3 (13% identical).
Diseases named in the same sentence as ENAH in open-access papers:
ENAH is named in the same sentence as 36 diseases in open-access papers, as found by Europe PMC text mining. Sharing a sentence is not in itself a finding about the gene and the disease. The quoted sentences say what the papers report.
breast carcinoma (17 papers, 2010 to 2023). "Likewise, ENAH deficiency inhibited cell invasion, and metastasis, thus inhibiting the progression of breast cancer." (PMID 32698859, 2020). "Recent studies have shown the upregulated expression of ENAH in many human cancer types, namely breast cancer, melanoma, pancreatic cancer, and gastric cancer." (PMID 36832196, 2023). "In a recent study, the exosomal level of ENAH was significantly higher in BC patients compared to healthy controls, thus providing a novel approach for early breast cancer screening." (PMID 36832196, 2023). "KIAA1522 potentiates metastasis in esophageal carcinoma and breast cancer cells, potentially linking ENAH and KIAA1522 in tumor progression." (PMID 35076015, 2022). "As reported, ENAH is identified as a tumor promoter in gastric cancer, esophageal carcinoma and breast cancer." (PMID 35030977, 2022). "Extensive studies have demonstrated upregulation of ENAH in many tumors, including breast carcinoma, cervical carcinoma, colorectal carcinoma, and hepatocellular carcinoma." (PMID 35012558, 2022). "ENAH, alone, promotes haptotaxis of breast cancer cells through fibronectin gradients and regulates translation of specific mRNAs in developing axons, implicating it in functions beyond its role in actin polymerization." (PMID 34854809, 2021). "We examined focal adhesion maturation as a readout of ENAH function in MCF7 breast cancer cells, which express significant levels of ENAH." (PMID 34854809, 2021). "Of note, expression of just one of these basal B-specific splice variants, which are CTNND1, ENAH and PLOD2, is sufficient to lower the disease-specific survival rate of basal B-like breast cancer patients compared to basal A-like." (PMID 33845831, 2021). "ENAH was recently reported to be up-regulated in many human cancers, including breast cancer and melanoma." (PMID 29069803, 2017). "While ENAH expression was recently reported to be increased in breast cancer, hepatocellular carcinoma, and melanoma, its role in GC remained undefined." (PMID 29069803, 2017). "For example, the activity of ENAH, a very important molecule in breast cancer transformation and invasiveness, decreases during mammary gland development, but increases in breast tumors." (PMID 26919109, 2016). "The overexpression of ENAH has previously only been reported in breast cancer." (PMID 20187983, 2010). "We found several targets of QKI and RBFOX1, including FLNB, SLK, USO1, ENAH, ESYT2, NUMB and ARHGEF1, to be among the most differentially spliced genes in basal B breast cancer cell lines." (PMID 30059005, 2018). "Paralog-specific Ena/VASP inhibitors could have higher therapeutic potential, given the antagonistic roles of ENAH and EVL in promoting and suppressing breast cancer metastasis." (PMID 34854809, 2021). "In addition, whereas ENAH and VASP promote the invasive potential of migratory breast cancer cells, EVL suppresses breast cancer invasion." (PMID 34854809, 2021). "For example, considering that AUC > 0.75 supports good biomarker feasibility, ENAH and RAD51 could be repurposed for breast cancer diagnosis usage." (PMID 29050243, 2017). "The role of ENAH in cancer metastasis has motivated work to identify inhibitors of its EVH1-mediated interactions, and extensive structure-based design and chemical optimization recently led to a high-affinity molecule (KD = 120 nM) that reduced breast cancer cell extravasation in a zebrafish model." (PMID 34854809, 2021).
gastric cancer (9 papers, 2010 to 2024). A primary or metastatic malignant neoplasm involving the stomach. "Among proteins with increased levels in OSCC, ENAH has been selected for investigation due to its correlation with worse survival in gastric cancer patients, and its role in the actin-dependent cell migration." (PMID 39511483, 2024). "A prior study concluded that ENAH was expressed at high levels in gastric cancer, while the upregulation of ENAH aggravated the proliferation and migration of gastric cancer in vitro and in vivo, which was consistent with the results of our study." (PMID 32698859, 2020). "We found significantly increased mRNA (P = 0.0283) and protein (P = 0.0301) expression of ENAH in gastric cancer tissues." (PMID 29069803, 2017). "We also analyzed data of 155 gastric cancer cases from The Cancer Genome Atlas (TCGA) and found that ENAH expression significantly correlated with age (P = 0.003), T stage (P = 0.023) and prognosis (P = 0.05)." (PMID 29069803, 2017). "Studies suggested that ENAH may play a promoting role in the development of gastric cancer and may be a valuable prognostic marker for patients with primary gastric adenocarcinoma." (PMID 33101383, 2020). "Additionally, ENAH is highly expressed in gastric cancer and apparently enables its development, highlighting its potential as a prognostic marker for gastric cancer patients." (PMID 32698859, 2020). "Furthermore, the function of ENAH in cell proliferation, colony formation, cell migration and invasion of gastric cancer cells was analyzed in vitro." (PMID 29069803, 2017). "Our research suggests that ENAH might play promoting functions in carcinogenesis and progression of gastric cancer, and may serve as a valuable prognostic marker for primary gastric adenocarcinoma patients." (PMID 29069803, 2017). "OSMR and ENAH showed overexpression in samples with copy number gains compared to samples with normal copy number (p < 0.05, FC 2.4 for OSMR and 3.8 for ENAH) as well as in gastric cancers in general compared to the normal gastric tissues (p < 0.001, FC 3.4 for OSMR and 8.4 for ENAH)." (PMID 20187983, 2010). "ENAH, one of the 18 upregulated proteins, was selected to verify its role in promoting OSCC progression, as it has been proven to participate in the formation of actin-dependent filopodia and the progression of gastric cancer." (PMID 39511483, 2024). "In addition to ERBB2 and PERLD1, the TRAC analysis also identified five novel genes, CYP3A4, ENAH, MMP9, PTPRA, and OSMR, which have not been reported as gained and overexpressed in gastric cancer before." (PMID 20187983, 2010).
hepatocellular carcinoma (6 papers, 2017 to 2025). A malignant tumor that arises from hepatocytes. "High ENAH expression has been verified to be associated with poor prognosis in hepatocellular carcinoma (HCC)." (PMID 35030977, 2022). "Additionally, enabled homolog (ENAH), an actin-binding protein elevated in hepatocellular carcinoma tissues and cells, is linked to a poorer prognosis." (PMID 40271197, 2025). "In addition, ENAH expression is increased in hepatocellular carcinoma and is associated with tumor differentiation and clinical stage." (PMID 29069803, 2017). "ENAH expression was previously reported to correlate with tumor grade and vascular invasion in salivary tumors, and is associated with tumor differentiation and clinical stage hepatocellular carcinoma." (PMID 29069803, 2017). "In miR-139-5p, it suppressed the proliferation and migration of hepatocellular carcinoma cells by downregulating the expression of ENAH." (PMID 35495130, 2022). "Moreover, ENAH depletion was previously reported to suppressed migration, invasion and metastasis in hepatocellular carcinoma." (PMID 32698859, 2020). "Likewise, upregulated ENAH plays a tumor-promoting role in hepatocellular carcinoma." (PMID 32698859, 2020).
breast tumor (4 papers, 2010 to 2023). "In this study, the hybrid-based FS pipeline screened an optimal subset that includes three gene biomarkers, namely MAPK1, APOBEC3B, and ENAH, for earlier detection of primary breast tumors." (PMID 36832196, 2023). "To conclude, we propose that, using a robust hybrid FS method, the present study identified a robust and optimal set of three gene biomarkers (MAPK 1, APOBEC3B, and ENAH) for detecting the primary breast tumors of BC patients." (PMID 36832196, 2023). "In the real-time online primary breast tumor detector, the users can classify primary breast tumor samples from normal breast samples using the gene expression values of the genes, namely MAPK-1, APOBEC3B, and ENAH actin regulator (ENAH)." (PMID 36832196, 2023).
esophageal carcinoma (4 papers, 2022 to 2023). A primary or metastatic malignant neoplasm involving the esophagus. "For example, in esophageal carcinoma, circ0030018 was dramatically overexpressed and served as a sponge for miR‐599 to promote cancer progression via regulating the expression of ENAH." (PMID 37250146, 2023).
esophageal squamous cell carcinoma (4 papers, 2020 to 2025). Esophageal squamous cell carcinoma (ESCC) is a type of esophageal carcinoma (EC) that can affect any part of the esophagus, but is usually located in the upper or middle third. "In contrast, EVs from hUC-MSCs have been shown to retard the progression of esophageal squamous cell carcinoma by carrying miR-375, which downregulates Enabled homolog (ENAH)." (PMID 41254732, 2025). "HucMSC-EVs deliver miRNA-375 to downregulate ENAH and inhibit the initiation and progression of esophageal squamous cell carcinoma (ESCC)." (PMID 35915054, 2022). "MiR-375 subsequently decreased the expression of ENAH and repressed the invasion and migration of esophageal squamous cell carcinoma (ESCC) cells by regulating the expression levels of EMT-related proteins (E-cadherin, N-cadherin and Snail)." (PMID 39161894, 2024).
colorectal cancer (2 papers, 2016 to 2022). A primary or metastatic malignant neoplasm that affects the colon or rectum. "Increased ENAH/Mena expression levels correlate with invasiveness of breast and salivary gland tumors, and are also seen in colorectal cancer and in polyps with high grade dysplasia." (PMID 26847345, 2016).
gastric adenocarcinoma (2 papers, 2017 to 2020). "This study aimed to investigate the expression and function of ENAH in primary gastric adenocarcinoma, and its prognostic significance." (PMID 29069803, 2017). "In conclusion, we have demonstrated amplified expression of ENAH in gastric adenocarcinoma and its correlation with a more malignant phenotype and unfavorable prognosis in a large number of clinical GC samples." (PMID 29069803, 2017). "Moderately and poorly differentiated gastric adenocarcinoma showed high ENAH expression." (PMID 29069803, 2017). "Noncancerous gastric mucosa and well-differentiated gastric adenocarcinoma showed low ENAH expression." (PMID 29069803, 2017).
invasive breast carcinoma (2 papers, 2007 to 2022). A carcinoma that infiltrates the breast parenchyma. "Like LASP-1, ENAH is not detectable in benign breast epithelium, but is weakly expressed in low-risk benign diseases like fibroadenomas and strongly expressed in invasive breast cancers." (PMID 17956604, 2007).
oral cancer (2 papers, 2024 to 2025). "The upregulation of ENAH through a PI3K/AKT/β-catenin signaling cascade enhances oral cancer cell migration and growth via the ITGB5/Src axis." (PMID 39511483, 2024). "ENAH expression enhances cell proliferation and mobility by upregulating integrin β5 in oral cancer cells." (PMID 39511483, 2024). "Notably, NNMT and ENAH have been shown to enhance the proliferative and tumorigenic potential of oral cancer cells, while TNC contributes to an immune-suppressive tumor microenvironment in OSCC." (PMID 41044643, 2025). "Since EMAH has been identified as a transcriptional target of the Wnt/β-catenin pathway in hepatoma cells and this pathway is frequently involved in the pathogenesis of oral cancer, we aimed to ascertain whether Wnt/β-catenin plays a regulatory role in ENAH expression in OSCC cells." (PMID 39511483, 2024).
pancreatic cancer (2 papers, 2023 to 2024). "ENAH participates in modulating invasion and metastasis of cancer cells and is found to be dysregulated in breast, gastric, lung, and pancreatic cancers." (PMID 39511483, 2024).
cardiomyopathies (1 paper, 2023). "Similarly, RNA-binding motif protein 24 (RBM24) regulates a subset of genes associated with cardiomyopathies such as sarcomere z-disc genes TTN, nebulette (NEBL), and enah actin regulator (ENAH)." (PMID 38132114, 2023).
dilated cardiomyopathy (1 paper, 2010). Cardiomyopathy which is characterized by dilation and contractile dysfunction of the left and right ventricles. "Also, combined disruption of the localization of ENAH and VASP in cardiac intercalated disks causes dilated cardiomyopathy and early postnatal lethality, whereas VASP knock-out mice show no cardiac abnormalities." (PMID 20565797, 2010).
keloid (1 paper, 2022). An irregularly shaped, elevated mark on the skin caused by deposits of excessive amounts of collagen during wound healing. "Therefore, we speculate that XLOC_000587 in keloids may further regulate related signaling pathways by increasing the expression of ENAH to promote EMT and the invasive development of keloids." (PMID 35012558, 2022). "The lncRNA, XLOC_000587 may promote cell proliferation and migration by enhancing the expression of ENAH, while AF268386 may facilitate the invasive growth of keloids by upregulating DDR2." (PMID 35012558, 2022). "In particular, lncRNA XLOC_000587 may participate in cell proliferation and migration by enhancing the expression of ENAH, and AF268386 may accelerate the invasive development of keloids by upregulating DDR2." (PMID 35012558, 2022).
liver cancer (1 paper, 2024). An epithelial or non-epithelial malignant neoplasm that arises from the liver. "Moreover, ENAH has been revealed as a transcriptional target of the Wnt/β-catenin pathway in gastric, colorectal, breast, and liver cancer cell lines." (PMID 39511483, 2024).
medulloblastoma (1 paper, 2020). A malignant, invasive embryonal neoplasm arising from the cerebellum. "The roles of ACTL6A, EIF4A3, ENAH, and UMPS in medulloblastoma had not been reported." (PMID 33101383, 2020).
meningioma (1 paper, 2017). A generally slow growing tumor attached to the dura mater. "We also detected amplification of both enabled homolog (ENAH) and poly [ADP-ribose] polymerase 1 (PARP1) in CH157-MN, although these genes have not previously been implicated in meningiomas tumorigenesis." (PMID 28552950, 2017).
neuroblastoma (1 paper, 2006). Neuroblastoma (NB) is the most common solid, extracranial childhood tumor. "Interestingly, when compared with neuroblasts, the neuroblastomas have more genes in common with the self-renewing neural stem cells (535 versus 145), among others the neurogenesis genes ASCL1, GSS, STAT3, UTP11L, ENAH, APBB2, CDK5RAP2, and LARGE." (PMID 16989664, 2006).
osteosarcoma (1 paper, 2016). A usually aggressive malignant bone-forming mesenchymal neoplasm, predominantly affecting adolescents and young adults. "The level of ENAH expression, however, was significantly reduced in the metastatic osteosarcoma samples compared the osteoblasts (p = 0.0002) and primary osteosarcoma samples (p = 0.004)." (PMID 27966608, 2016). "Given the increased expression of ENAH in human osteosarcoma samples, transposon insertion profiles for Enah were evaluated from the Sleeping Beauty derived tumors." (PMID 27966608, 2016). "Metastatic samples had either 1.8 greater SRGAP2C: SRGAP2 transcript ratio (n = 2) or a two-fold reduction of ENAH compared to primary osteosarcoma samples (n = 5)." (PMID 27966608, 2016).
T-cell lymphomas (1 paper, 2015). "Regarding a shared activated phenotype for T-cell lymphomas, of the observed upregulated genes, two (CAV1 and ENAH) have been implicated in cytoskeletal remodeling (and therefore, cellular migration and immune synapse formation) following TCR-ligation." (PMID 26566034, 2015).